CACNG1 (calcium voltage-gated channel auxiliary subunit gamma 1)
Description:
Regulatory subunit of the voltage-gated calcium channel that gives rise to L-type calcium currents in skeletal muscle. Regulates channel inactivation kinetics.
Synonyms: CACNLG
Tractability: Small molecule: an approved drug acts on it; a high-quality ligand is known; it belongs to a druggable protein family. Antibody: UniProt places it where antibodies can reach, with medium confidence; UniProt predicts a signal peptide or a membrane-spanning region; its Gene Ontology location is reachable by antibodies, with medium confidence.
Gene: Protein-coding gene on chromosome 17 (67,044,554 to 67,056,797, forward strand). Ensembl gene ENSG00000108878.
Subcellular location: Cell membrane, sarcolemma
Gene Ontology:
Molecular function: protein binding; calcium channel regulator activity; voltage-gated calcium channel activity
Biological process: calcium ion transmembrane transport; positive regulation of muscle contraction; regulation of calcium ion transmembrane transport via high voltage-gated calcium channel; calcium ion transport
Cellular component: L-type voltage-gated calcium channel complex; plasma membrane; sarcolemma; T-tubule; membrane; voltage-gated calcium channel complex
Genetic constraint (gnomAD): Loss-of-function variants: 20 observed, 22.05 expected, observed/expected ratio (o/e) 0.91, 90% interval 0.64 to 1.32. The upper end of that interval is the gene's LOEUF score, 1.32, which puts it in group 5 of 6, group 1 being the genes least tolerant of losing a copy. Missense variants: 291 observed, 316.92 expected, observed/expected ratio (o/e) 0.92, 90% interval 0.83 to 1.01. Synonymous variants: 127 observed, 133.23 expected, observed/expected ratio (o/e) 0.95, 90% interval 0.82 to 1.11.
Homologues: Orthologues: chimpanzee CACNG1 (99% identical), macaque CACNG1 (98% identical), pig CACNG1 (89% identical), dog CACNG1 (87% identical), guinea pig CACNG1 (86% identical), mouse Cacng1 (86% identical), rat Cacng1 (85% identical), zebrafish cacng1b (71% identical), zebrafish cacng1a (66% identical), tropical clawed frog cacng1 (64% identical), rabbit CACNG1 (54% identical). Paralogues in human: CACNG6 (39% identical).
Diseases named in the same sentence as CACNG1 in open-access papers:
CACNG1 is named in the same sentence as 9 diseases in open-access papers, as found by Europe PMC text mining. Sharing a sentence is not in itself a finding about the gene and the disease. The quoted sentences say what the papers report.
postmenopausal osteoporosis (2 papers, 2019 to 2023). Metabolic disorder associated with fractures of the femoral neck, vertebrae, and distal forearm. "In another study, CACNG1 is thought to participate in modulating postmenopausal osteoporosis via Ca2+ regulation during muscle contraction." (PMID 36833449, 2023). "Because patients with PO often have hypercalciuria with normal blood Ca2+ levels, CACNG1 is thought to be involved in the mechanisms of postmenopausal osteoporosis through Ca2+ regulation during muscle contraction." (PMID 31064048, 2019). "Gene expression profiles suggested that SMAD4, CACNG1, and TRIM63 may have vital roles in the molecular mechanism of postmenopausal osteoporosis and that miR-331 may be a potential biomarker for postmenopausal osteoporosis, however, further studies are required." (PMID 31064048, 2019).
hearing loss (1 paper, 2022). "A de novo heterozygous variant of CACNG1 was identified as the candidate cause of the sporadic hearing loss in family 1669." (PMID 35248088, 2022). "The other five genes (SVEP1, CACNG1, GTPBP4, PCNX2, and TBC1D8) were categorized as Tier 4 genes, with no known association with hearing loss." (PMID 35248088, 2022).
Malignant hyperthermia (1 paper, 2014). Malignant hyperthermia is characterized by a rapid increase in temperature to 39-42 degrees C. Malignant hyperthermia may occur in response to either inhalational anesthetics such as halothane, to muscle relaxants such as succinylcholine, or to exercise. "However, CACNG1, CACNB1 and CACNA2D1 encode for subunits of the DHPR calcium channel, which is in direct contact and regulating RYR1 in skeletal muscle, and one mutation in the channel subunit CACNA1S of DHPR was linked to malignant hyperthermia." (PMID 25353622, 2014).
cancer (1 paper, 2022). A tumor composed of atypical neoplastic, often pleomorphic cells that invade other tissues.
CACNG1 also shares sentences with these, for which no sentence is quoted: brain diseases (1 paper); breast carcinoma (1); dilated cardiomyopathy (1); epilepsy (1); Glucose intolerance (1).